GATA3 (GATA binding protein 3)
Diseases named in the same sentence as GATA3 in open-access papers (continued):
Sharing a sentence is not in itself a finding about the gene and the disease.
cancer (continued). "It regulates the specification and differentiation of various tissue types, and immunohistochemistry for GATA3 expression is primarily used in surgical pathology diagnosis for carcinomas originating from breast or urothelial tissue." (PMID 33680920, 2020). "For example, the top 15 SGA-FIs (ranked according to the FDR p values of overlapping DEG sets) that share DEGs with PIK3CA include PTEN, CDH1, ERBB2, and GATA3, which are known cancer drivers, and their connections agree with existing knowledge." (PMID 31276486, 2019). "Mutations in six genes (NCOR1, GATA3, CDH1, ATM, AKT1, and PTEN) were significantly correlated with the corresponding expression levels, and were enriched and involved in multiple cancer‐related pathways." (PMID 30883028, 2019). "Our present study also showed a tendency for a better prognosis in cancers with FOXA1 or GATA3 expression." (PMID 31500577, 2019). "Further RNA-sequencing (RNA-seq) analysis of a TCGA dataset composed of 981 patient samples suggests that UTX and GATA3 were expressed similarity at substantially lower levels in the samples of basal-subtype carcinomas than luminal-subtype carcinomas." (PMID 31685800, 2019). "A high level of “luminal-like” genes such as AR and GATA3 in LAR-TNBC subtype has a relatively favorable prognosis compared to tumors expressing cancer stem cell markers." (PMID 30034618, 2018). "As MBC is a rare cancer with limited numbers of available tumors for genomic studies, ChIP-seq analyses for some factors including PR and GATA3 were performed on relatively low number of tumors." (PMID 29396493, 2018). "Determining the molecular rationale for why specific GATA3 sites are critical to phenotype and outcome thus becomes an important goal for deciphering the role of GATA3 in cancer." (PMID 29535312, 2018). "ONCOMINE analysis revealed that GATA3 mRNA expression was significantly higher in BC than normal samples across a wide variety of datasets in different cancer types." (PMID 28423734, 2017). "Taken together, we demonstrate that vWF expression in ECs of LAC is elevated by the cancer cell-derived secretome through enhanced GATA3-mediated transcription." (PMID 29299165, 2017). "Increased expression of GATA3 has been shown to be a good prognosis marker in other types of cancer such as breast." (PMID 28379958, 2017). "Such cancer type–specific associations were also seen for PIK3CA, KRAS, GATA3, CTCF, CDH1, and ARIDA1." (PMID 29125844, 2017). "Our findings suggest that GATA3 stabilizes HIF-1α to enhance cancer invasiveness under hypoxia and support the GATA3/HIF-1α axis as a potential therapeutic target for cancer treatment." (PMID 28263977, 2017). "Due to the varied roles of GATA3 on different tissue types, it is important but also time/effect-consuming to find the regulatory network of GATA3 in each type of cancer separately." (PMID 28415601, 2017). "Local immune cell subsets were measured on formalin-fixed, paraffin-embedded cancer tissue by immunohistochemistry to examine expression of transcription factors that control Th1 (T-bet) and Th2-type (GATA3) immunity." (PMID 28005163, 2017).
cancer (continued). "But more significantly, our study has discovered that gene mutation and gene amplification in two cancer driver genes, PIK3CA and GATA3, are correlated oppositely to the IDC histologic changes." (PMID 27283966, 2016). "Given the capacity of GATA3 to catalyze cellular reprogramming relevant to cancer biology, characterization of the impact of cancer-specific mutations in this pioneering TF represents a field or enquiry with major clinical ramifications." (PMID 26922637, 2016). "Recent studies have investigated the significance of GATA3 expression in patients with various malignant tumors." (PMID 27249072, 2016). "To confirm the mammary origin of the cancer cells we employed estrogen receptors and GATA3 immunostains." (PMID 27672468, 2016). "The function of GATA3 has been previously reported in breast cancer tumorigenesis, but there are few reports of a link between T-bet and cancer formation." (PMID 27589565, 2016). "GATA3 is a sensitive urothelial immunomarker staining in 86% of patients, and it is also specific as the only additional carcinomas it stains positive for are breast (94%) and to a much lower frequency endometrial (2%)." (PMID 26634162, 2015). "This clustering suggests regulatory roles for the carboxyl terminus of GATA3 and that impairment of these functions can provide a growth advantage to cancer cells." (PMID 24758297, 2014). "Combined, the differences in GATA3 target genes and responses indicate that alterations in GATA3 regulatory effect depend on the cellular settings (that is, normal versus cancer cells), possibly reflecting other transcription factors expressed in the cell." (PMID 25410484, 2014). "GATA binding protein 3 (GATA3) was recently proposed to function as a tumor suppressor gene in some types of human cancer." (PMID 24504018, 2014). "We previously found that the transcription factors MEF2D and GATA3, as well as the histone deacetylases HDAC3 and HDAC9, regulate BRM expression in BRM-deficient cancer cell lines." (PMID 24913006, 2014). "GATA3 target genes were identified in normal- and luminal cancer- mammary cells by ChIP-seq, followed by examination of the effects of GATA3 expressions and mutations on tumorigenesis-associated genes and processes." (PMID 25410484, 2014). "While none of these proteins was found to be mutated in BRM-deficient cancer cell lines, HDAC9 and GATA3 were overexpressed in both lung cancer-derived cell lines and primary lung tumors, as well as in rhabdoid cell lines and primary tumors." (PMID 25774356, 2014). "Accordingly, a group of genes that we identified by ChIP-seq and that responded differentially to GATA3 (for example, BMP2, ERBB4 and KIF16B) are linked to proliferation and maintenance of normal or cancer stem cells." (PMID 25410484, 2014). "Immunohistochemically, the carcinoma cells reacted strongly and diffusely with cytokeratin 7, estrogen and progesterone receptors, and GATA3." (PMID 25400965, 2014). "Microarray data clearly showed that Gata3 was specifically expressed in luminal subtype cancer cells." (PMID 23284647, 2012).
cancer (continued). "Gene-expression profiling has shown that GATA3 is highly expressed in luminal A and B subtypes of cancer and closely related to ERα." (PMID 19638208, 2009). "Infection of the MMTV-PyMT carcinomas with GATA3 upregulated markers of differentiation and resulted in a dramatic 27-fold reduction in lung metasases." (PMID 18533032, 2008). "In addition, previous studies documented a significantly lower GATA3 expression in cancer, for example, of the skin, cervix and vagina, compared with their respective premalignant lesions." (PMID 41300727, 2025). "GATA3 is recognized as an oncogenic transcription factor in several cancers." (PMID 41585508, 2025). "This confirmed that GATA3 positively regulated the transcription of SLC7A11 in cancer cells." (PMID 39800682, 2025). "Overall, no homozygous GATA3 deletion was detected and heterozygous GATA3 deletion was only observed in 1.1%; of 1,432 pT2-4 tumors without any association to cancer progression." (PMID 39979991, 2025). "Although the role of GATA3 is well established in many cancers, its specific function in the progression of early‐stage CMF remains unclear." (PMID 40856420, 2025). "Moreover, these two SBS subtypes differed in somatic mutations in several cancer driver genes, including higher mutation frequency of ERBB2, GATA3 and FGFR4, and lower frequency of DMD, INHBA, OGDHL, PLEKHG5 and RYR2 in subtype 3 than in subtype 1 (P < 0.05)." (PMID 40858906, 2025). "GATA3 deletion was unrelated to clinicopathological parameters in pT2-4 carcinomas." (PMID 39979991, 2025). "The first pathology report found the following results: Cytokeratin 7 (CK7) - positive within carcinoma cells in underlying lymphovascular spaces; CK20 - appeared negative within a few remaining neoplastic carcinoma cells; and GATA3 - weak positivity within neoplastic carcinoma cells." (PMID 40125201, 2025). "Deregulation of the GATA3 has been reported in various cancers." (PMID 38173189, 2024). "The molecular mechanisms underlying the selection of GATA3 upregulation in well-differentiated epithelium-like BCs rather than invasive cancers have been elucidated so far." (PMID 39768217, 2024). "Absence of GATA3/Upk1a/b staining was significantly linked to poor patient survival in the subgroup of 126 pT4 carcinomas (p = 0.0004) but not in pT2 and pT3 cancers." (PMID 37777995, 2024). "In contrast, GATA3 and IL-10 dominated to suppress the Th1 phenotype toward cancer progression." (PMID 38279220, 2024). "For example, targeting GATA3 in combination with other pathways involved in cancer progression could provide a more comprehensive approach to treatment." (PMID 39768217, 2024). "Finally, expression patterns of the pioneer factor GATA3 in normal mammary glands and carcinomas are comparable between rats and humans, in contrast to the low expression of GATA3 observed in mouse mammary epithelium." (PMID 38913216, 2024). "Furthermore, a progressive loss of Upk1a/b expression during stage progression and a prognostic role of the combination GATA3/Upk1a/Upk1b in pT4 carcinomas is evident." (PMID 37777995, 2024). "Again, the expression of FRA1 in these cancers was also negatively correlated with that of GATA3." (PMID 37353480, 2023). "Overall, the most common additional mutations acquired during evolution were those affecting PIK3CA and GATA3, which showed no clear correlations with cancer clones, although they are among the most frequent mutations in breast cancer." (PMID 37495687, 2023). "In CK7 + /CK20 − cases, ER positivity and GATA3 positivity in ER-negative cases primarily directed clinicians to complete radiological imaging investigations of the breast as a possible site of cancer origin, especially in patients with axillary lymph node metastases." (PMID 36346458, 2023). "Therefore, GATA3 IHC is useful for differentiating UC phenotypes and for the differential diagnosis between UC and other malignant tumors." (PMID 37629741, 2023).
cancer (continued). "GATA-3 immunostaining frequency was equivalent to that of ER: the degree of GATA-3 expression in tumors well differentiated was significantly higher in the group of benign tumors and well-differentiated carcinomas, while its expression was lower in aggressive tumors (p < 0.05)." (PMID 37483298, 2023). "GATA3 is a transcription factor that regulates the development of different tissues and GATA3 is expressed in carcinomas of multiple tissue types, such as mammary, urothelial, anal, cervical, lung, and, especially, salivary glands (classic SDC and secretory carcinomas)." (PMID 37886914, 2023). "The correlations between GATA3 and the immunomodulators were heterogeneous in different cancers." (PMID 35647011, 2022). "Moreover, GATA3 transcriptionally inhibits Slug expression, thereby inhibits cancer cell proliferation, migration and invasion." (PMID 36685890, 2022). "In addition, we demonstrated that GATA3 was negatively correlated with the pan-cancer T-cell inflamed score (Spearman R = −0.46)." (PMID 35647011, 2022). "Pan-cancer analysis contributed to illustrating the immunological role of GATA3 and screening the types of cancers that may benefit from anti-GATA3 immunotherapy." (PMID 35647011, 2022). "To test this, we used CRISPR/Cas9 to knockout (KO) FOXA1 or GATA3 in HCC1954 cancer cells." (PMID 35331302, 2022). "We examined additionally whether GATA3 or Hnf4a affects the malignant features and tumorigenicity of cancer cells." (PMID 34595169, 2021). "GATA3 was both up-regulated and down-regulated in different cancer types." (PMID 34301206, 2021). "For example, we suppose that retinoid receptors, MAX and GATA3, as demonstrated in other types of cancer, could interact with the zinc finger protein YY1 that is known to modify chromatin structure and interact with insulators elements such as CTCF." (PMID 34449674, 2021). "Furthermore, the widespread expression of GATA3 in numerous cancers demonstrate the potential for GATA3-targeted manipulation for clinical interventions." (PMID 34099719, 2021). "In this report, we used p18, Brca1, and Gata3 singly and doubly deficient mouse models as well as human BRCA1 proficient and deficient cancer cells to determine the mechanisms underlying the role of BRCA1 in the regulation of GATA3 in mammary tumorigenesis and metastasis." (PMID 34373738, 2021). "However, additional examination of GATA3 and its contribution to mitochondrial biogenesis in cancer is needed to confirm this." (PMID 34099719, 2021). "Through the study it was concluded that the highly prospected pioneer TFs in BC, including FOXA1, TLE1, PBX1, and GATA3, possess the potential therapeutic significance and further innovations in the field could yield targeted therapy in cancer treatment." (PMID 36046086, 2021). "(DAVIS) GATA3 and AR correlation can be used in GATA3-positive tumors of unknown origin to distinguish metastatic GATA3-positive carcinoma of breast origin from urothelial origin." (PMID 33915941, 2021). "Such classification is achieved based on genomic and transcriptomic analyses, which point to differential expression of specific markers among tumors: the basal cytokeratins KRT5/KRT6A and KRT14, as hallmarks of basal BlCa, and the luminal markers FOXA1 and GATA3, as hallmarks of luminal cancer." (PMID 32758253, 2020). "Overexpressed GATA3 further increased the apoptosis rate of Oxa-treated cancer cells (p < 0.01)." (PMID 32760217, 2020). "Hundreds of reports describe the cancer-inhibiting implications of GATA3." (PMID 31856849, 2019). "We applied BioTarget to assess the activity of TBX21 and GATA3 pathways in cancers." (PMID 31227749, 2019). "Bioinformatics analysis revealed that SNPs in six genes (NCOR1, GATA3, CDH1, ATM, AKT1, and PTEN) were significantly associated with the corresponding expression levels and were involved in multiple pathways involved in cancer development." (PMID 30883028, 2019).
cancer (continued). "GATA3 expression was elevated in M2 CM-treated compared with M1 CM-treated cancer cells." (PMID 30218063, 2018). "Considering this crucial function, it is therefore not surprising that Gata3 has been implicated in a number of different cancer types." (PMID 30463912, 2018). "To assess the contribution of HIF-1α to the GATA3-mediated cancer cell invasiveness, we knocked down endogenous HIF-1α or expressed N-HIF-1α in Mock or GATA3 stable transfectants and then carried out transwell migration and Matrigel invasion assays under hypoxia." (PMID 28263977, 2017). "In accordance, GATA3 promotes cancer cell invasiveness in vitro and in vivo." (PMID 28263977, 2017). "Therefore, it is important to find the regulatory network of GATA3 in each type of cancer separately, including B-ALL." (PMID 28415601, 2017). "Here, we report that GATA3 functions as an HIF-1α regulator to promote cancer cell invasiveness." (PMID 28263977, 2017). "Also, an up-regulated expression of tumor suppressors such as Rb, GATA3 and PTEN associated with cancer cell proliferation was evident." (PMID 29246124, 2017). "In addition, it is worth mentioning that our results also show that GATA3 enhances cancer cell invasiveness under normoxia." (PMID 28263977, 2017). "The contribution of GATA3 to cancer is, in contrast, poorly understood." (PMID 27588951, 2016). "Thus, with four out of the five antibodies tested by our laboratory and the HPA, nuclear GATA3 staining was seen in colon epithelial and cancer cells." (PMID 26097693, 2015). "GATA3 directly upregulates ER-alpha and other proto-oncogenes suggesting that it may promote tumorigenesis in luminal cancer." (PMID 26467651, 2015). "Conversely, in luminal cancer cells, GATA3 expression led to proliferation of TICs." (PMID 25410484, 2014). "Additionally there was a significant trend for early neoplasias to have a much higher fraction of cells staining positive for FOXA1 and GATA3 than normal, with positive cell fractions similar to those observed in cancer." (PMID 24887547, 2014). "This suggests that transcript 13741 may have a role in the ER/FOXA1/GATA3 pathway being activated in early neoplasias and maintaining elevated levels within cancer." (PMID 24887547, 2014). "Our findings that ER, FOXA1, and GATA3 are all expressed at levels comparable to their matched IDC suggest that the oncogenic nature of ER pathway activation is established in the earliest stages of cancer development." (PMID 24887547, 2014). "The dual activities of GATA3 are exemplified by its effect on normal/cancer stem cell populations." (PMID 25410484, 2014). "Women who had ER-positive, PgR-positive, or GATA3-positive cancer were infrequently diagnosed first with lung metastases (20 (14.1%) of 142 vs. 21 (23.3%) of 90, P = 0.072; 13 (12.3%) of 106 vs. 29 (23.4%) of 124, P = 0.030; and 21 (13.9%) of 151 vs. 16 (23.5%) of 68, P = 0.079, respectively)." (PMID 21914172, 2011). "It indicated that METTL3 could negatively regulate the expression of GATA3 in cancer cells." (PMID 39800682, 2025). "However, some rare TNBC subtypes may still express GATA3, complicating the understanding of its role in these cancers." (PMID 39768217, 2024).